AHR (aryl hydrocarbon receptor)
Diseases named in the same sentence as AHR in open-access papers (continued):
Sharing a sentence is not in itself a finding about the gene and the disease.
lung carcinoma (continued). "Identifying the most sensitive biological responses induced by AhR may provide important information on the main mechanisms driving lung cancer development at relatively low PM-exposure levels encountered in outdoor air." (PMID 37696458, 2023). "In addition, ligand-induced AhR signals in lung cancer cells upregulate the expression of osteopontin (OPN) through AhR and NF-κB pathways interplay, and inhibition of AhR by the antagonist desmosflavone (DMF) reverses these effects." (PMID 37241719, 2023). "Deregulation of PG metabolism could also contribute to multiple roles that the AhR has been proposed to play in lung cancer development and metastasis." (PMID 35203356, 2022). "The optimal decision tree for never smokers consists of 7 AhR/Wnt-variants and only two lung cancer variants." (PMID 35101137, 2022). "AhR could maintain GSK3β in an active form, thus suppressing epithelial-mesenchymal transition in lung cancer cells, which may be used to alleviate lung fibrosis." (PMID 35656117, 2022). "Kyn treatment in the HFLs co-culture system also promoted the nuclear entry of AhR, indicating that Kyn produced by CAFs could mediate the activation of AhR signals in lung cancer." (PMID 35831824, 2022). "More importantly, testing AhR expression or Kyn level might help to predict the EGFR TKIs responses in lung cancer." (PMID 35831824, 2022). "The MEK inhibitor trametinib was more effective in lung-cancer cells that strongly express AhR." (PMID 33451095, 2021). "Collectively, these findings indicate that inhibition of UCHL3 may effectively eliminate lung cancer stem cell properties by promoting AhR destabilization." (PMID 32546741, 2020). "The aryl hydrocarbon receptor (AhR) signaling pathway, activated by polycyclic aromatic hydrocarbons (PAHs) present in tobacco, is another important important mechanism, particularly in cigarette smoke induced lung cancer." (PMID 31776385, 2019). "A pro-oncogenic role for AhR over-expression in lung cancer may be a consequence of an AhR-dependent promotion of cell proliferation, cell-cycle progression, cell migration and cell survival." (PMID 30563036, 2018). "Lung carcinogenesis has also been hypothesized to be via crosstalk with nuclear factor (erythroid-derived 2)-like 2 and ER, thereby providing effective targets for the AhR to prevent and treat lung cancer." (PMID 29487603, 2018). "The AhR is expressed at high levels and is chronically active in blood tumors, such as T-cell leukemia and lymphoma, as well as in solid tumors such as glioblastoma, ovarian cancer, lung cancer, liver cancer, and head and neck carcinomas." (PMID 29487603, 2018). "However, the role of the AhR in diseases such as chronic obstructive pulmonary disease (COPD)—a respiratory illness caused predominately by cigarette smoking—and lung cancer remains largely unexplored." (PMID 30563036, 2018). "Taken together, we found that AhR regulates BNIP3 degradation to disturb the autophagy process in lung cancer cells, which may result in decreased cellular EMT." (PMID 28195146, 2017). "The cell shapes were affected by changing AhR protein level in these two lung cancer cells." (PMID 28195146, 2017). "The unbiased discovery of the AHR pathway as well as pathways involved in hypoxia (HIF3A) and mucosa-mediated clearance of lung airways (FOXJ1), demonstrates the ability of SEPIRA to identify early and potentially causal pathways in lung cancer development." (PMID 29262847, 2017). "Overexpression of AhR accelerates the proliferation of lung cancer A549 cells." (PMID 27050278, 2016). "We found that CXCL13 was a direct target of AhR, and deficiency in CXCL13 or its receptor, CXCR5, abrogated BaP-induced lung cancer, while an anti-CXCR5 antibody significantly inhibited lung cancer cell migration." (PMID 26565418, 2015).
lung carcinoma (continued). "The relevance of the IDO-AHR-IL-6-STAT3 transcriptional circuit is underscored by the finding that high expression of its members IDO, STAT3 and the AHR target gene CYP1B1 is associated with reduced relapse-free survival in lung cancer patients." (PMID 24657910, 2014). "AHR-KYN activation has been confirmed in human brain tumors, melanoma, renal cancer, B-cell lymphoma, Ewing sarcoma, bladder carcinoma, cervix carcinoma, colorectal carcinoma, lung carcinoma, and ovarian carcinoma, and is associated with tumor progression and drug resistance." (PMID 40332338, 2025). "Therefore, the activation of Wnt/β-catenin, KRAS, and AHR pathways due to impaired kidney function may play a substantial role in the development of lung cancer." (PMID 38549355, 2024). "Furthermore, AhR expression was diminished in the metastatic lung tumors, suggesting that AhR may have tumor suppressor-like activity for human lung cancer." (PMID 38518996, 2024). "Mechanistically, long-term exposure of lung cancer cells to PM2.5 may promote lung cancer progression through activation of the Aryl hydrocarbon receptor (AhR) and epidermal growth factor receptor (EGFR), which boosts the Serine protease pathway transmembrane 2 (TMPRSS2)-IL8 pathway." (PMID 38299096, 2023). "Notably, the authors discovered that the activation of AhR by omeprazole drove the suppression of lung cancer cells’ growth via an AhR-dependent induction of the expression of activating transcription factor 4 (ATF4) and upregulation of asparagine synthetase (ASNS)." (PMID 37106727, 2023). "However, this suggested framework for AhR signaling in lung cancer may provide a guidance for future studies and development of AOPs for AhR in lung cancer from exposure to ambient air PM2.5 and combustion PM." (PMID 37696458, 2023). "However, it should be noted that proliferation and colony formation of lung cancer cells with KRAS mutations may be less affected by PM2.5 exposure than lung cancer cells harboring tEGFR mutations, and AhR has also been reported to suppress KRAS-driven NSCLC." (PMID 37696458, 2023). "This AhR-kynurenine-PD-1 pathway may also be activated in air pollution induced lung cancer." (PMID 37696458, 2023). "We aimed to assess a possible association of AhR pathway and Wnt signalling cascade with LC within the large-scale series of cases and controls of European descent hold by the International Lung Cancer Consortium (ILCCO)/Integrative analysis of Lung Cancer Etiology and Risk (INTEGRAL)." (PMID 35101137, 2022). "Moreover, AHR activation by benzo[a]pyrene promotes cell migration, invasion, and epithelial–mesenchymal transition by upregulating the expression of long non-coding RNA in lung cancer." (PMID 36292946, 2022). "Furthermore, it was demonstrated that administration of 2,3,7,8-tetrachlorodibenzo-p-dioxin (TCDD), which is an obesogenic-related ligand of the AHR, in omega-3 fatty acids-fed mice reduced the growth rates of lung carcinoma-derived tumors and inhibited their metastasis to lung and liver." (PMID 36457890, 2022). "Finally, UCHL3 functions to promote tumor growth and lung cancer stem-like properties through AhR." (PMID 32546741, 2020). "AhR may also act through PD-L1 independent mechanisms in lung cancer cells." (PMID 30850589, 2019). "Hence, AhR has a central role in lung carcinogenesis and may serve as a target for chemoprevention and treatment of lung cancer." (PMID 30850589, 2019). "Thus, the role of the AHR-pathway in lung cancer etiology is unclear." (PMID 29262847, 2017). "This stabilization was shown to increase the binding of AHR to the promoter regions of the stemness genes such as ABCG2, KLF4, and cMYC, promoting tumor growth and enhancing lung cancer stem-like properties." (PMID 40303305, 2025).
lung carcinoma (continued). "The role of AHR and NRF2 in regulating ferroptosis in breast and lung cancer cells is unclear, but AHR has been shown to promote the development of non-small cell lung cancer (NSCLC) by inducing the expression of SLC7A11, a key regulator of ferroptosis." (PMID 38982523, 2024). "AhR mediates BaP-induced production of a chemokine CXCL13, the knockout of which significantly inhibits BaP-initiated lung cancer." (PMID 39042313, 2024). "In lung cancer, an autocrine signaling loop mechanism was deciphered, which involved KYN activation of AhR, followed sequentially AhR-mediated IL-6 upregulation, STAT3 stimulation, and KYN-producing IDO1 induction." (PMID 39211042, 2024). "Then, activation of the AhR-TMPRSS2-IL-18 pathway promotes cell proliferation, invasion, and metastasis in lung cancer models." (PMID 38299096, 2023). "Ubiquitin C-terminal hydrolase L3 (UCHL3) stabilizes aryl hydrocarbon receptor (AhR) by its deubiquitylation and subsequently increases ABCG2 to promote stem-like properties in lung cancer." (PMID 36694209, 2023). "AhR nuclear expression also correlated with TMPRSS2 and IL18 expression and cancer stage in human lung cancer tissue." (PMID 37696458, 2023). "Our research demonstrated that the interaction between AHR and PLK1, the role of DIO2, and thyroid hormones were significant factors in lung cancer cells spread." (PMID 37988371, 2023). "Clinical correlation of TMPRSS2 expression with age, sex, nuclear AhR, IL18, and overall stage in 25 lung cancer patientsa." (PMID 36975376, 2023). "Epidemiological studies have shown that BaPy activates AhR, a transcription factor contained in all tissues, including bronchial epithelial cells, and also has a major role in the development of COPD and lung cancer." (PMID 37763058, 2023). "Recent studies have suggested a potential connection between AHR and PD1/PDL1 regulation in the context of lung cancer." (PMID 37760608, 2023). "A recent study has indicated that the AhR agonist 11-Cl-BBQ (11-chloro-7H-benzimidazo[2,1-a]benzo[de]iso-quinolin-7-one) prompts anti-proliferative effects in H460 lung cancer cells." (PMID 37241719, 2023). "Next, we detected the expression of AhR pathway genes (IDO1, AhR, CYP1A1, and CYP1B1) in SARS-CoV-2–infected and mock-infected human lung cancer cells (H1299 and Calu-3)." (PMID 37256962, 2023). "In this study, we show that long‐term exposure of lung cancer cells to PM2.5 can activate AhR to promote the expression of TMPRSS2 and IL18 and promote lung cancer progression." (PMID 36975376, 2023). "Increasing studies have highlighted the importance of both the AhR and HIF-1α signaling pathways in the development of lung cancer." (PMID 35473600, 2022). "Blockade of AhR efficiently improved the outcome of EGFR TKIs, which provides a novel strategy for clinical lung cancer treatment." (PMID 35831824, 2022). "For example, TGF-β activation downregulates the AHR gene at the transcriptional level in human A549 lung carcinoma cells, whereas, in human HepG2 hepatocarcinoma cells, TGF-β activation increases AHR promoter activity." (PMID 35163440, 2022). "Radianspenes C and D, and dahliane D, reduced expression of AhR, PD-L1, ICOSL, and GITRL proteins by H1975 lung cancer cells, as well as exerting anti-proliferative effects." (PMID 36160406, 2022). "All these findings are suggesting a combination of AhR inhibitor and EGFR TKIs as a novel therapeutic strategy to treat lung cancers." (PMID 35831824, 2022). "The mechanisms of toxicity of HAHs involve the AHR, but PAHs in part mediate their action by inducing CYP1A1, which, in turn, bioactivates the PAHs to DNA-reactive metabolites, resulting in cancers of the lung and other extra-hepatic organs." (PMID 35163440, 2022). "In this paper, we found a new mechanism of AhR regulation and functional mechanism by which UCHL3 promotes lung cancer progression and stemness." (PMID 32546741, 2020).
lung carcinoma (continued). "We next verified that the AHR activator omeprazole induced expression of ASNS and ATF4 in three different lung cancer cell lines, H1975, A549, and H1299." (PMID 33214553, 2020). "Compounds reactivating suppressed AHR and/or AHR-regulated anti-metastatic programs may provide leads for the development of novel and specific pharmacologic strategies to prevent metastatic progression and increase survival in patients with early-stage lung cancer." (PMID 33214553, 2020). "AhR protein levels were markedly upregulated in ADC and SCC lung cancer tissues compared with corresponding paracancerous normal tissues." (PMID 32546741, 2020). "PAHs are exogenous ligands that bind to the AhR, which reacts with PAHs via Phase I CYP enzymes to sequentially influence the initiation, promotion, and progression of lung cancer." (PMID 29487603, 2018). "Taken together, these data suggest that the differences in cell motility based on AhR levels is mediated by autophagy, which involves crosstalk between AhR and EMT in lung cancer cells." (PMID 28195146, 2017). "Herein, we investigated the degradation pathway of BNIP3 in an immunoprecipitation assay to evaluate the relationship between AhR and BNIP3 during autophagy in lung cancer." (PMID 28195146, 2017). "has been shown to interact with [MIM: 126110], which binds to Aryl Hydrocarbon Receptor ( [MIM: 600253]), and the pathway has been recently shown to be activated upon binding of various exogenous chemicals from cigarette smoke and might link to lung cancer risk." (PMID 22536319, 2012). "Liu Shuang and colleagues investigated lncRNA-microRNA interactions, chromatin modifiers, and ferroptosis in lung cancer, as well as the oncogenic role of GINS4, the tumor-suppressive function of GPR162 in radiotherapy, the impact of AhR on NSCLC, and the targeting of USP8 in HCC treatment." (PMID 39944353, 2024). "Notably, the crosstalk between AhR and JAK/STAT signaling cascades blunts anti-tumor immune responses and promotes malignancies such as lung cancer, melanoma, glioblastoma, and oral squamous cell carcinoma." (PMID 39211042, 2024). "Overall, AhR may regulate iron, GSH, and lipid ROS levels in lung cancer cells by promoting SLC7A11 transcription, thereby inhibiting lung cancer cell ferroptosis and promoting non-small cell lung cancer development." (PMID 37056388, 2023). "Long‐term exposure to PM2.5 could promote tumor progression in lung cancer through activation of EGFR and AhR to enhance the TMPRSS2‐IL18 pathway." (PMID 36975376, 2023). "Taking all together, we hypothesized that the interaction of AHR and PLK1 was important in LUAD and thus focused on this lung cancer subtype for our study." (PMID 37988371, 2023). "Nuclear localization of AhR has been reported to be more common in lung cancer from women, non-smokers, adenocarcinoma and NSCLC patients with the EGFR exon 19 (E746–750A) deletion." (PMID 37696458, 2023). "As discussed in the present review, AhR and PAHs appear to affect many of the same responses in the lungs and a corresponding AOP could likely be developed for lung cancer development from PM2.5 and combustion particles." (PMID 37696458, 2023). "AhR plays a crucial role in the metabolism of B[a]P by affecting the expression of CYP 450 and the regulation of numerous genes’ expression that contributes to the initiation, promotion, and progression of lung cancer." (PMID 35683027, 2022). "The inactivation of the AHR-pathway, possibly initiated and mediated by hypomethylation and overexpression of AHRR, could be an important early step in lung cancer development." (PMID 32963246, 2020). "Furthermore, in stable UCHL3-knockdown H358 cells, expression of the AhR protein was downregulated, indicating that UCHL3 plays a key role in regulating AhR expression in lung cancer." (PMID 32546741, 2020).
lung carcinoma (continued). "The expression of PD-L1 and AhR in lung cancer tissues of smoker patients was higher than in nonsmoker patients, and these molecules co-localize on lung cancer cells." (PMID 30850589, 2019). "Specifically, our work points towards inactivation of the AHR pathway as the more fundamental event underlying smoking-mediated lung carcinogenesis, instead of AHRR hypomethylation which is not observed in lung cancer." (PMID 29262847, 2017). "IDO was demonstrated to drive IL-6 production in lung cancer and metastatic breast cancer, while, downstream product of IDO metabolism, kynurenic acid, can potentiate IL-6 production by the aryl hydrocarbon receptor (AHR)." (PMID 29296206, 2017). "Instead, the observed gradual inactivation of AHR from dysplasia to LCIS and LSCC suggests that the onset of lung cancer may select for cells for which AHR is inactivated." (PMID 29262847, 2017). "We identify TFs, such as AHR, which become inactivated in the earliest stages of lung cancer and which, unlike AHRR hypomethylation, are also inactivated in lung cancer itself." (PMID 29262847, 2017). "Our results suggest that MEOX2, HDAC9, TWIST1, AhR and EVX1 overexpression from the 7p21 locus may be novel lung cancer or NSCLC tumor markers." (PMID 25460568, 2014). "Recent works have shown that, even without its environmental ligands, AHR is overexpressed and constitutively active in a variety of sporadic human cancers, especially mammary, prostate, gastric and lung cancers." (PMID 25019383, 2014). "Hence, the importance of AhR-Cav1 crosstalk likely extends beyond regulation of EGFR and warrants further studies into the role of non-genomic AhR signaling in ordered membrane microdomains for development of lung cancer." (PMID 37696458, 2023). "Thus, it is unequivocal that AHR is tumor suppressive, rather than oncogenic, at least in human lung cancer." (PMID 37151890, 2023). "Therefore, AhR plays a role in chronic bronchitis, asthma, and chronic obstructive pulmonary disease (COPD), and has also been shown to play an important role in the development of lung cancer." (PMID 35683027, 2022). "The Aryl hydrocarbon receptor (AhR), which binds to polycyclic aromatic hydrocarbons (PAHs), and halogenated aromatic hydrocarbons (HAHs) can activate the expression of CYP1A1, CYP1A2, and CYP1B1; consequently, these enzymes have the capacity to activate procarcinogens resulting in lung cancer." (PMID 34685098, 2021). "Mechanistically, the AhR-dependent promotion of several pro-oncogenic signaling pathways (e.g., JAK2-Src interaction) is independent of the transcriptional activities of the AhR, suggesting the involvement of non-canonical AhR signaling in the promotion of lung cancer progression." (PMID 30563036, 2018). "Moreover, AhR could play specific roles in different types of lung cancers, where some express high AhR levels and others do not, and some are induced by AhR, while others are suppressed by AhR activity." (PMID 37696458, 2023). "Although the potential role of AhR-induced Ca2+-responses in lung cancer development remains to be clarified, this underscores that models developed to assess AhR REP based on XRE/DRE driven reporters may not account for the non-classical effects of AhR ligands." (PMID 37696458, 2023). "However, while these observations are compatible with the involvement of sex steroid hormones, the interaction between PAHs and ER in lung cancer development remains elusive, and AhR-ER crosstalk has so far not been explored in lung cells with EGFR driver mutations." (PMID 37696458, 2023). "Our findings about the role of the AhR in the control of AA metabolism may have implications not only for inflammatory reaction within alveoli, but also for our understanding of the development of lung cancer." (PMID 35203356, 2022).
lung carcinoma (continued). "To explore the role of TOX in carcinogenesis, we analyzed the correlation between AHR and TOX expression using RNA-seq data from human lung cancer, which revealed a negative correlation between AHR and TOX." (PMID 40303305, 2025). "Interestingly, while most of the NSCLC patients studied were current smokers, cancer cells with AhR and AhRR expression, which is activated by the many components/carcinogens of tobacco smoke and, therefore, may be used as a biomarker of lung cancer development, were not identified in our work." (PMID 39199657, 2024).